IL13 (interleukin 13)
Diseases named in the same sentence as IL13 in open-access papers (continued):
Sharing a sentence is not in itself a finding about the gene and the disease.
Autoimmunity (16 papers, 2010 to 2025). The occurrence of an immune reaction against the organism's own cells or tissues. "Although it is unclear whether αζDKO Tfr-cells were impaired in suppressive function, they gained expression of Tfh-associated cytokine Il21 as well as Th2-associated cytokines Il4 and Il13, which might have contributed to the IgG1/IgE-predominant antibodies and autoimmunity in Treg-αζDKO mice." (PMID 39651265, 2025). "Treatment with OA also reduced the indices of inflammation and autoimmunity in colon tissues, (i.e., increased TNFα, IL-1β, IL-23, IL-17A, and KC; and reduced IL-13, IL-33, and IL-25)." (PMID 33246492, 2020). "Another study reported that the addition of Gal-3BP induced suppression of IL-4, IL-5, and IL-13, Th2-type cytokines related to autoimmunity." (PMID 31402917, 2019). "A set of key interleukins, namely pro-inflammatory IL-6, immunoregulatory IL-10, anti-inflammatory IL-13, and autoimmunity-related IL-17, were assayed by ELISA." (PMID 24236103, 2013). "Suppressive effects of iNKT cells in autoimmunity are generally thought to be caused by production of the Th2 cytokines IL4 and IL-13, while their immunostimulatory effects in other tumor systems are typically IFNγ-dependent." (PMID 22880059, 2012). "Interestingly, bullous pemphigoid, another type of autoimmune blistering disease similar to, but distinct from, PV, is also featured by a Th2-predominant autoimmunity, showing significantly increased serum IL-4 and IL-13 as compared with healthy individuals." (PMID 29541411, 2018). "The preferential production of IL-13 by human iNKT cells activated with weak agonists may have important implications in the therapeutic manipulation of these cells for treatment of autoimmunity or other inflammatory conditions." (PMID 21179412, 2010). "Co-existing Th1 and Th2 cytokine elevations (IFN-γ/TNF-α and IL-4/IL-13, respectively) may indicate pathogenic bystander activation, mirroring patterns observed in autoimmune disorders where nonspecific inflammatory responses enforce the immune dysregulation." (PMID 40806391, 2025). "IL-5, IL-6, IL-13, IL-17, IL-23, and TNF-α are targetable with biologics developed for spontaneous autoimmunity, and our data broadly support the prospective investigation of these inhibitors for patients with irAEs." (PMID 39403935, 2024). "Another study showed a dependency of accelerated autoimmunity and beta cell destruction on increased IFN-γ, IL-12, and IL-17 and decreased IL-4, IL-6, and IL-13 in pediatric patients with T1D." (PMID 37893217, 2023).
childhood asthma (16 papers, 2010 to 2025). "In the present study, the genotype distribution of the +2044GA polymorphism of IL-13 showed a statistically significant association with childhood asthma (pooled p-value <0.001)." (PMID 38699097, 2024). "The present study aims to investigate the genetic aberrations, specifically single nucleotide polymorphisms (SNPs) of IL-4 and IL-13, and their association with childhood asthma and its severity." (PMID 38699097, 2024). "Additionally, in Xinjiang Uygur, several studies have found that IL-4 and IL-13 gene polymorphisms are associated with childhood asthma." (PMID 36313877, 2022). "Another multicentre prospective study reported that higher nasopharyngeal airway type 2 cytokine (IL-4, IL-5, IL-13, and TSLP) levels in infants with HRV infection alone were associated with a greater risk of developing childhood asthma." (PMID 40852413, 2025). "Larger studies are warranted to investigate the combined effects of the SNPs in the IL-4/IL-13 signaling pathway and the interaction with mold exposure on childhood asthma." (PMID 33810791, 2021). "During pregnancy, the maternal ratios of IFN-γ/IL-13 and IFN-γ/IL-4 are associated with a lower prevalence of childhood asthma." (PMID 34409053, 2021). "Five genes were found to be associated with self-reported childhood asthma in COPDGene: IL1RL1, IL13, LINC01149, near GSDMB, and in the C11orf30-LRRC32 region." (PMID 30373671, 2018). "The rationale is that early intervention, particularly with therapies blocking IL-4 and IL-13, might be attractive in childhood asthma, which is often driven by allergen sensitization, eosinophilia, and T2 immunity." (PMID 40486460, 2025). "IL-4 and IL-13 are the critical cytokines that regulate the switching from Immunoglobulin M (IgM) to IgE in activated B lymphocytes and the differentiation of Th2 cells, which is the pathogenesis of allergic inflammation or childhood asthma." (PMID 33810791, 2021). "Relationship of CD4+/IL-13+ T cells with disease activity suggests that this lymphocyte subset may have a prominent role in childhood asthma." (PMID 21197090, 2010). "Indeed, a recent report with detailed immune assessment of 514 infants 18 months of age corroborate exaggerated systemic immunity, in particular blood neutrophils and IL-13 producing T cells, at the time of enrollment to predict both transient and persistent childhood asthma." (PMID 33717182, 2021). "Our GWAS dataset supported an association between identical SNPs reported in ORMDL3/GSDMB/GSDMA, IL5/RAD50/IL13, HLA-DR/DQ, and SMAD3 and pediatric asthma (P<0.05)." (PMID 21814517, 2011). "Moreover, the IL4Ra and INSIG2 gene combination interacted with GSTP1, STAT6, ADRB2, ADRB3, IL13 and EPHX1 exon 3 to reveal a high training-balanced accuracy above 58.38% in childhood asthma." (PMID 22355322, 2012).
lymphedema (16 papers, 2015 to 2025). Excess fluid collection in tissues, causing swelling. "In fact, we found that inhibiting Th2 differentiation using monoclonal antibodies directed against interleukin-4 (IL-4) or interleukin-13 (IL-13) markedly decreased fibrosis, leading to resolution of pathologies associated with lymphedema and restoration of lymphatic function." (PMID 26039103, 2015). "Inflammatory mediators such as IL-4, IL-13, TGF-β, and LTB4 are implicated in various pathways that promote lymphedema progression." (PMID 40026487, 2025). "We have previously shown that the inhibition of Th2 differentiation using IL-4- or IL-13-neutralizing antibodies is an effective means of treating lymphedema and improving lymphatic function." (PMID 40426856, 2025). "Neutralizing IFN-γ enhanced inflammatory lymphangiogenesis regardless of VEGF-A and VEGF-C levels, while blocking Th2 cytokines, IL-4 and IL-13, reduced lymphedema and improved lymphatic function." (PMID 40655011, 2025). "Th2 cells, a type of helper T cell, mainly secrete cytokines such as IL-4 and IL-13 during the progression of secondary lymphedema." (PMID 40766782, 2025). "Specifically, infiltration of Th2 CD4+ T cells characterized by signature cytokines such as IL-4, IL-5, and IL-13 promotes lymphedema but Treg cells inhibit the development of lymphedema." (PMID 37940849, 2023). "Based on this pathophysiology, the efficacy of pharmacotherapy (tacrolimus, anti-IL-4/IL-13 antibody, or fingolimod) and cell-based therapy for lymphedema has been demonstrated in animal models and pilot studies." (PMID 35886961, 2022). "In one study, neutralizing antibodies against interleukin-4 (IL-4) and interleukin-13 (IL-13) were used to treat lymphedema in a mouse model." (PMID 28232732, 2017). "Furthermore, the inhibition of Type 2 T helper (Th2) cytokines by blocking interleukin (IL)-4 or IL-13 has been found to prevent the initiation and progression of lymphedema." (PMID 39941140, 2025). "The inhibition of Th2 differentiation with IL-4- or IL-13-neutralizing antibodies prevents the initiation and progression of lymphedema by inhibiting tissue fibrosis and improving lymphatic function in another mouse tail lymphedema model." (PMID 35886961, 2022). "Additionally, a report detailed the efficacy of monthly intravenous QBX258 infusion, a combination of two monoclonal antibodies neutralizing IL-4 and IL-13, in eight patients with breast cancer-related lymphedema." (PMID 35886961, 2022). "Additionally, Th2 helper cells are required for the development of lymphedema and Th2 cytokines; IL-4, and IL-13 are anti-lymphangiogenic, adding to the pathophysiology of lymphedema." (PMID 32344864, 2020). "Consequently, when these same animals were treated with IL-4 or IL-13 neutralizing antibodies, lymphedema was prevented." (PMID 32268536, 2020). "Th2 cells may also be involved in lymphedema pathogenesis as neutralization of two cytokines produced by these cells, IL-4 and IL-13, in a mouse model of secondary lymphedema promoted lymphatic function and restricted fibrosis." (PMID 30761143, 2019). "Similarly, treatment of mice with neutralizing antibodies against IL4 or IL13, cytokines necessary for differentiation of naïve Th cells to Th2 phenotype, not only prevented the development of lymphedema in preclinical mouse models but also treated lymphedema once it was established." (PMID 34571811, 2021). "This hypothesis is supported by the fact that inhibition of Th2 differentiation with antibodies that neutralize IL4 or IL13, cytokines necessary for naïve T helper cell differentiation along the Th2 lineage, is highly effective in preventing the development of lymphedema in mouse models." (PMID 30936872, 2019). "For instance, CD4+ T cells such as Th1 and Th2 immune paradigms can trigger the release of IL-4, IL-13, and TGF-β1 across tissues and they can control collagen deposition and fibrosis in lymphedema." (PMID 37267206, 2023).
lymphedema (continued). "Recent studies suggest that Th2 cells play a key role in the pathology of secondary lymphedema by elaborating cytokines such as IL4 and IL13." (PMID 34571811, 2021). "Lymphedematous skin from clinical biopsy specimens and mouse models of lymphedema are infiltrated with large numbers of CD4+ cells that co-express interferon gamma (IFN-γ; putative Th1 cells) and CD4+ cells that co-express interleukin 4 (IL4) or IL13 (putative Th2 cells)." (PMID 30936872, 2019). "Therefore, since the increase in Il1rl1 indicates the induced infiltration of ST2+ cells, IL-33 may be involved in the infiltration of other ST2+ cells besides IL-13-expressing ILC2, leading to CD4+ T cell and Treg cell infiltration during lymphedema development." (PMID 39941140, 2025).
respiratory allergy (16 papers, 2009 to 2025). "Specifically, the type 2 cytokine IL-13 is known as the central mediator of lung inflammation caused by respiratory allergies and less severe COVID-19 infection." (PMID 38060612, 2023). "Further research on thioredoxin revealed the mechanism of the therapeutic effect of thioredoxin on airway allergy through the downregulation of interleukin-13 (IL-13) expression and eosinophil activity." (PMID 39403377, 2024). "The TIGIT+ ILC2s have low proliferative activity and low mRNA expression of Il5 and Il13, indicating that TIGIT+ IL-10+ exhausted-like ILC2s can be induced by severe acute and chronic airway allergy even in mice with intact Runx protein function." (PMID 38788198, 2024). "Interleukin 13 (IL-13), predominately secreted by T helper 2 (TH2) cells, has been found to contribute to airway allergies and suppress BPIFA1 expression in nasal epithelial cells." (PMID 26646664, 2015). "Interleukin 13 (IL-13), a cytokine predominately secreted by TH2, has been found to contribute to airway allergies and to suppress BPIFA1 expression in nasal epithelial cells." (PMID 26646664, 2015). "In the murine model of airway allergy, IL-10-producing ILC2s produce high levels of IL-5 and IL-13 compared with non-IL-10 producers." (PMID 38788198, 2024). "The gene expression of IL-13, a cytokine known to contribute to airway allergies, was not induced either." (PMID 28640227, 2017).
co-infection (15 papers, 2009 to 2023). "Our results verify reports illustrating that M. bovis co-infection increase helminth parasite burden and correlates with decreased IL-4 and IL-13 cytokine production." (PMID 24433309, 2014). "In contrast, levels of IL-4 and IL-13 were greatly reduced at times after co-infection compared with Nb-only infected mice." (PMID 25474738, 2014). "Using our modelling approach we showed that IL5 and IL13 had complementary abilities against helminths and contributed to parasite reduction both in single and co-infection." (PMID 22253585, 2012). "The authors showed that co-infection of mice with M. sympodialis and S. aureus or p. aeruginosa increased allergic and inflammatory responses by significantly increasing the level of IL-5, IL-13 and IL-17, respectively." (PMID 34682276, 2021). "The expression of IL-13 was predominant in dogs infected with D. repens, and the expression of STAT6 and regulatory IL-10 predominated in dogs with co-infection." (PMID 36739305, 2023). "and C. perfringens co-infection was highly correlated with IFN-α, IFN-γ, IL-4, IL-13, IL-16, LITAF, TGF-β4 and TNFSF15 in the jejunum, indicating that Th2 type cytokines mainly participated in avian NE." (PMID 37240767, 2023). "IL-13 expression was predominant in dogs infected with D. repens, and STAT6 and IL-10 predominated in dogs with co-infections." (PMID 36739305, 2023). "In contrast, this co-infection in RAG2 females downregulated expression of several cytokines such as Il-1β, Il-17A, Ifnγ, Tnfα, and Il-13 only at 10 WPI, but increased transcription of colonic Il-22 at 21 WPI." (PMID 33255175, 2020). "Compared with P. berghei ANKA-mono-infection group, the co-infection group showed a significantly lower level of IFN-γ on day 5 and day 8 pi and significantly higher levels of IL-4, IL-5 and IL-13 on day 3, 5, 8 pi." (PMID 24034228, 2013). "To examine the immune profile of individuals with co-infection, we compared the concentration of 15 immune markers (IL-1β, IL-6, IL-8, TNF-α, IL-7, G-CSF, MCP-1/CCL2, MIP-1-α/CCL3, IL-12, IFN-γ, IL-13, IL-17A, GM-CSF, IL-10, and TGF-β1) among the three groups using Kruskal-Wallis ANOVA." (PMID 27128316, 2016). "Furthermore, during co-infection diminished, but not absent, Th2 cytokine secretion was observed and IL-4 and IL-13 were detectable after stimulation of splenocytes with killed STm." (PMID 25474738, 2014). "Those with Plasmodium mono-infection had higher levels of IL-4, IL-6, IL-10, IL-12, IL-13, IL-17A, IFN-γ, and MIP1-α/CCL3 compared with DENV mono-infection or co-infection; those with Plasmodium mono-infection had more cough than those with DENV mono-infection." (PMID 27128316, 2016). "Compared to P. berghei-mono, mice in the co-infection-100c group had significantly lower levels of IFN-γ on days 5 and 8 pi and higher levels of IL-4, IL-5, IL-13 and TGF-β on days 3, 5, and 8 pi, while no significant changes in IL-10 levels were observed between the two groups." (PMID 24670210, 2014).
Crohn disease (15 papers, 2008 to 2024). A gastrointestinal disorder characterized by chronic inflammation involving all layers of the intestinal wall, noncaseating granulomas affecting the intestinal wall and regional lymph nodes, and transmural fibrosis. "Similarly, patients expressing a more active variant of IL-13, with a reduced affinity to the IL-13α2 decoy receptor, had a lower risk of developing Crohn's disease." (PMID 34078488, 2021). "Crohn's disease is principally a Th1 and IFN-γ driven condition whilst ulcerative colitis is associated with increased Th2 cytokines such as IL-5 and IL-13." (PMID 34078488, 2021). "These suggest that drugs targeting the IL-13 pathway should be explored in patients with Crohn’s disease to try to reduce the potential for fibrotic strictures." (PMID 23300643, 2012). "The symptoms observed in Crohn's disease result from an altered intestinal immune system response that triggers the excessive release of cytokines such as TNF-α, IFN-γ, IL-12, IL-13, and IL-17, secreted by Th1 cells." (PMID 30254638, 2018).
lymphoma (15 papers, 2011 to 2025). A malignant (clonal) proliferation of B- lymphocytes or T- lymphocytes which involves the lymph nodes, bone marrow and/or extranodal sites. "In NHL, STAT6 is essential for IL-4 and IL-13 signaling, which supports Th2-mediated immune responses and aids in the survival and growth of lymphoma cells." (PMID 40321894, 2025). "As both discordant lymphomas of HL and peripheral T cell lymphoma are known to overexpress IL-13, future studies should evaluate the effect of anti-IL-13 therapy in these settings." (PMID 38398754, 2024). "IL-13 plays a crucial role in disease pathogenesis in different types of lymphomas, acting as an autocrine growth factor in Hodgkin‘s lymphoma and extranodal natural killer/T cell lymphoma." (PMID 38607023, 2024). "The tumor-promoting M2 LAMs can be induced under the influence of the cytokines (IL-4, IL-13, IL-10 and M-CSF) produced by the lymphoma cells and the microenvironment." (PMID 34527580, 2021). "Our investigations into the IL-4/IL-13 axis indicated that global expression of IL-4Rα was required for optimal pro-tumor effects of apoptotic lymphoma cells, as well as optimal TAM accumulation." (PMID 25702581, 2015). "Thus, our study expands the role of IL13 from an autocrine growth factor to a lymphoma‐secreted factor that mediates ECM remodeling and immunosuppression by HL‐educated Mφ, which in turn facilitates the dissemination of lymphoma cells." (PMID 31825135, 2020). "Thus, IL13 seems to be not only involved in the autocrine support of HL cells but also in rebuilding the lymphoma microenvironment through Mφ differentiation and upregulation of CD206." (PMID 31825135, 2020). "Expression of B cell-stimulatory cytokines IL-1β, IL-6, IL-10, IL-12p40, IL-13 and TNFα and HIV proteins p17, gp120 and nef were elevated in the Tg mice with lymphoma." (PMID 23985023, 2013). "Expression of phosphorylated STAT6 without IL4/IL13 transcription has been demonstrated in PMBL, suggesting that STAT6 activation in these lymphomas is not due to an autocrine IL4/IL13 secretion." (PMID 37835560, 2023). "Our study highlights the role of Jak/STAT signaling and, particularly, the capacity of IL13 to upregulate CD206 expression on Mφ, thus expanding its role from an autocrine growth factor in HL to a lymphoma‐secreted factor capable of modulating the tumor microenvironment." (PMID 31825135, 2020). "Furthermore, in a study published soon afterward, it was shown that most CHL patients exhibited expression of IL-13, whereas this trait was either observed in none or fewer than 50% of patients with other forms of lymphoma, such as DLBCL." (PMID 35685639, 2022).
rhinitis (15 papers, 2011 to 2024). An inflammation of the mucous membrane lining the nose, usually associated with nasal discharge. "It has been elucidated that SNP-SNP interactions between GATA3 and IL13 polymorphisms can influence the risk of childhood rhinitis." (PMID 21738793, 2011). "Treatment of HNECs with IL-4 and IL-13, which are highly concentrated in the nasal epithelium of rhinitis patients, decreases the expression of ZO-1 and Occludin, components of tight junctions." (PMID 39108557, 2024). "It is noteworthy that nanobody H5, applied to the apical air side of HNECs of rhinitis patients, shows statistically superior performance in blocking the dual signaling of IL-4/IL-13 compared to dupilumab." (PMID 39108557, 2024). "Allergic rhinitis, eosinophilic rhinosinusitis, Rhinitis, asthma, and atopic dermatitis are allergic diseases controlled type 2 inflammatory cytokine such as IL-4 and IL-13." (PMID 39108557, 2024). "Nasal biopsies of rhinitis patients showed increased IL-4, IL-5, IL-13 mRNA expression suggesting a Th2 cytokine profile." (PMID 24116013, 2013). "Therefore, we used HNEpCs to investigate the mechanisms underlying the anti-rhinitis activity of CSLW and found that CSLW significantly inhibited the accumulation of eosinophils and upregulation of periostin, MUC5AC, and ROS in IL-4- and IL-13-stimulated HNEpCs in a concentration-dependent manner." (PMID 36421442, 2022).